MYBPC3 (myosin binding protein C3)
Diseases named in the same sentence as MYBPC3 in open-access papers (continued):
Sharing a sentence is not in itself a finding about the gene and the disease.
cardiomyopathy (continued). "Therefore, the American College of Veterinary Internal Medicine (ACVIM) consensus statement guidelines for classifying, diagnosing, and managing cardiomyopathies in cats recently recommended evaluating sarcomeric mutations of MYBPC3 before breeding to decrease this mutation in the feline population." (PMID 35400937, 2022). "Genetic analysis revealed two heterozygous missense variants in sarcomeric genes associated with inherited cardiomyopathies: MYH7: c.4186C>T (p.Arg1396Trp) and MYBPC3: c.2672G>A (p.Arg891Gln), both classified as variants of uncertain significance." (PMID 41728227, 2026). "This has also been reported for other heterozygous cardiomyopathy gene models, such as Csrp3, Mybpc3, Myh7 and Ttn displaying phenotypes in homozygous settings only, whilst heterozygous animals showed no cardiac abnormalities." (PMID 40128237, 2025). "Patients with the PLN variant exhibited higher incidences of non-sustained ventricular arrhythmias compared to those with myosin-binding protein C3 (MYBPC3)/myosin heavy chain 7 (MYH7)-related cardiomyopathies." (PMID 39507141, 2024). "CRISPR-mediated gene editing ameliorates cardiac hypertrophy and improves cardiac function in a murine model of MYBPC3-related cardiomyopathy." (PMID 39857372, 2024). "Seven variants (41%) were detected in genes associated with cardiomyopathies including CSRP3, LAMA4, MYH6, MYBPC3, TNNI3, TNNI3K, and TNNT2." (PMID 39272661, 2024). "There was an excess burden of splice-disrupting variants in PKP2 (5.9%), FLNC (2.7%), TTN (2.8%), MYBPC3 (8.2%) and MYH7 (1.3%), in distinct cardiomyopathy subtypes, and KCNQ1 (3.6%) in long QT syndrome." (PMID 37821546, 2023). "These genes are associated with cardiomyopathy, familial hypertrophic, 4, or CMH4 (OMIM #115197) for MYBPC3, CMH1 (OMIM #192600) for MYH7, CMH3 (OMIM #115196) for TPM1, CMH2 (OMIM #115195) for TNNT2, and CMH7 (OMIM #613690) for TNNI3." (PMID 36555486, 2022). "Using 2DMBs with ContractQuant analysis allowed precise characterization of a cardiomyopathy hPSC-CM model with contractile kinetic dysregulation due to MYBPC3 ablation that reinforces key findings from biophysical studies." (PMID 34697315, 2021). "In particular, the KCNE1, MYBPC3, and AKAP9 genes that were associated with LQTS or cardiomyopathy would have been suspicious as genes associated with cause of death because of an AD mode of inheritance." (PMID 34728707, 2021). "Our result demonstrates for the first time that MYBPC3 complete deletion is an important disease mechanism in cardiomyopathy and emphasizes the importance of copy number variation analysis in patients clinically suspected of HCM." (PMID 31568709, 2020). "Studies of the genetic causes of LVNC have primarily identified variants in cardiomyopathy genes, including MYH7, MYBPC3 and TTN, with reported genetic testing yields between 17 and 41%5." (PMID 33082984, 2020). "It has been shown that TOF is genetically heterogeneous, and a subgroup is characterized by genetic alterations in other sarcomere genes known to be causative of cardiomyopathy, such as MYH7 and MYBPC3." (PMID 33033063, 2020). "A recent study found that approximately one-half of the patients with NCCM had a mutation in a cardiomyopathy gene, and mutations in the MYH7, MYBPC3, and TTN genes were the most prevalent." (PMID 30809538, 2019). "An intronic 25-bp deletion in MYBPC3 at 3′ region is associated with dilated (DCM) and hypertrophic (HCM) cardiomyopathies in Southeast Asia." (PMID 21915287, 2011).
cardiomyopathy (continued). "In April 2024, the ClinGen Cardiomyopathy Variant Curation Expert Panel (VCEP) adapted the ACMG/AMP criteria for eight of the sarcomeric genes (MYH7, MYBPC3, TNNI3, TNNT2, TPM1, ACTC1, MYL2, and MYL3), providing a refined framework for variant interpretation in these genes." (PMID 41357762, 2025). "Moreover, the contribution of a proteo-toxic response to cardiomyopathy has been documented for pathogenic variants in CSRP3 and MYBPC3 through in vitro experiments and mouse models." (PMID 33637999, 2021). "Although case reports and small case series have described severe early‐onset disease associated with compound or heterozygote sarcomeric gene variants, only one patient had a compound heterozygote variant in MYBPC3 and two further patients had an additional VUS in a cardiomyopathy‐associated gene." (PMID 34486247, 2021). "Besides the hub genes of MYBPC3, MYH7, and DSP, these subnetworks also include several genes that have been implicated in cardiomyopathy, such as TPM1, ACTC1, DES, TCAP, JUP, and DSG2." (PMID 32344918, 2020). "Next Generation Whole Genome sequencing was performed using DNA isolated from peripheral blood of a Maine Coon with cardiomyopathy that tested negative for the MYBPC3 A31P variant." (PMID 33304277, 2020). "By performing MCL clustering, we highlighted four subnetworks that could play significant roles in HCM, including one mtDNA-subnetwork and three cardiomyopathy-gene-centered networks: MYBPC3-, MYH7-, and DSP-subnetworks." (PMID 32344918, 2020). "Here, we use the largest registry of combined genetics and clinical data for HCM to date, the Sarcomeric Human Cardiomyopathy Registry1 (SHaRe), to generate an adjudicated and comprehensive compendium of MYBPC3 variation, analyze regional variation within MYBPC3, and correlate clinical phenotypes." (PMID 32841044, 2020). "Our results demonstrate that haploinsufficiency resulting from MYBPC3 complete deletion, potentially mediated by Alu recombination, is an important disease mechanism in cardiomyopathy and emphasizes the importance of copy number variation analysis in patients clinically suspected of HCM." (PMID 31568709, 2020). "In addition to SNVs, we filtered a 25-bp deletion (rs36212066) in intron 32 of MYBPC3 (cardiac myosin binding protein C), which was reported to be related with cardiomyopathies and present in populations of Indian origin with MAF ~4%." (PMID 29420653, 2018). "The other children of the proband (II-2 and II-3), while carrying the MYBPC3 mutation, did not develop signs of cardiomyopathy when assessed at a similar age." (PMID 28797094, 2017). "Increased myofilament Ca2+ sensitivity, as observed in three Mybpc3 cardiomyopathy mouse models (Mybpc3 KO and KI) developed by us and others, and in other animal models of HCM, could be an underlying cause of diastolic dysfunction." (PMID 27994558, 2016). "The aim of this study was to functionally test five intronic variants (MYBPC3-c.506-2A>C, MYBPC3-c.906-7G>T, MYBPC3-c.2308+3G>C, SCN5A-c.393-5C>A, and ACTC1-c.617-7T>C) found in five patients affected by inherited cardiomyopathies in the attempt to verify their pathogenic role." (PMID 27834932, 2016). "A founder mutation arising at about the 10th century in the MYBPC3 gene accounts for 8.4% of all HCM in center east France and results in a cardiomyopathy starting late and evolving slowly but with an apparent risk of sudden death similar to other sarcomeric mutations." (PMID 23140321, 2012). "In addition, the cardiomyopathy related MYH6-A1004S and the MYBPC3-A833T mutations were also found in one and two unrelated subjects with ASDII, respectively." (PMID 22194935, 2011). "Importantly, in addition to cilia-associated genes, we identified recessive variants in four genes previously implicated in cardiomyopathy (MYH6, UNC45B, MYO18B, and MYBPC3) that are expressed in embryonic cardiomyocytes; RGs in these genes contributed to left-sided CHD phenotypes." (PMID 40030011, 2025).
cardiomyopathy (continued). "Additionally, a frameshift-causing 25-base-pair deletion from intron 32 of MYBPC3, which was originally linked to HCM in two families, has been identified in 13.8% of patients with various inherited cardiomyopathies (including HCM and dilated and restrictive cardiomyopathy)." (PMID 37445689, 2023). "As the proband was negative for the A31P mutation in MYBPC3, we asked if any other variants could be traced to the proband’s cardiomyopathy." (PMID 33304277, 2020). "The same MYBPC3 mutation was previously reported in a Dutch family, where a severely affected index patient had compound heterozygous mutations in MYCBP3 but other family members carrying only p.G148R were either asymptomatic or developed cardiomyopathy late in life." (PMID 25210889, 2014). "Various gene therapies are currently in development, including those aimed at myosin-binding protein C3 (MYBPC3)-related cardiomyopathy (NCT05836259) and the use of antisense oligonucleotides for PLN-R14del cardiomyopathy." (PMID 39674807, 2025). "Notably, sarcomeric genes such as TNNI3, TNNT2, MYBPC3, and MYH7 are classically associated with HCM, but the findings obtained by the present review demonstrate their significant role in DCM as well, establishing them as shared genetic substrates between the two cardiomyopathies." (PMID 41374444, 2025). "For instance, after only seven days of MYBPC3 treatment, serum response factor (SRF) and S100A4, both of which are known to be elevated in cardiomyopathies, drastically decreased." (PMID 37445689, 2023). "Five genes account for the majority of genetically explained cardiomyopathy and long QT (MYH7, MYBPC3, KCNQ1, KCNH2, SCN5A), resulting in narrower prediction confidence intervals." (PMID 33046849, 2021). "Among 7,963 patients in the multicenter Sarcomeric Human Cardiomyopathy Registry (SHaRe), 120 unique missense VUS in MYBPC3 were identified." (PMID 33782553, 2021). "Furthermore, 2 of the 46 cardiomyopathy genes, CDH23 and myosin binding protein C (MYBPC3), were significantly enriched for rare functional coding variants, as revealed by mutation burden analysis." (PMID 39730912, 2025). "Genetic testing, including a targeted cardiomyopathy panel and whole exome sequencing, did not identify any pathogenic variants, including in MYH7 or MYBPC3." (PMID 40546560, 2025). "The review identified key gene variants affecting athletic performance: endurance (AMPD1, PPARGC1A), power (ACTN3, NOS3), strength (PPARG), and injury susceptibility (COL5A1, MMP3), while also examining inherited conditions like cardiomyopathies (MYH7, MYBPC3)." (PMID 40724525, 2025). "In this study, we observed rare P/LP/VUS+ variants in 4 genes associated with cardiomyopathy (MYH7, CRYAB, SCN5A, and MYBPC3) in individuals without a history of MI or HF and with extensive myocardial fibrosis indicated by CMR." (PMID 35265679, 2022). "In fact, this has already been demonstrated for the cardiomyopathy-related gene LMNA and MYBPC3." (PMID 34769381, 2021). "Missense, rather than truncating, variants in MYH7 and truncating, rather than missense, variants in MYBPC3 are well-documented to be the mutational classifications associated with HCM, instead of other cardiomyopathy subtypes." (PMID 32344918, 2020). "While HCM has been attributed to monogenic perturbations in sarcomeric genes, like MYBPC3 and MYH7, there is often dramatic phenotypic variability, even within a single family, with some family members having other cardiomyopathy subtypes, including DCM and ARVC, or hybrid phenotypes." (PMID 32344918, 2020). "Additional cluster 3 proteins categorized to cardiomyopathy and sarcomeric proteins exposed to constant mechanical stress, including Desmin (DES), dystrophin muscular dystrophy (DMD); myosin binding protein C, cardiac (MYBPC3); myosin light polypeptide 2 (MYL2); Titin (TTN) and phospholamban (PLN)." (PMID 36681760, 2023).
heart failure (42 papers, 2011 to 2026). Inability of the heart to pump blood at an adequate rate to meet tissue metabolic requirements. "At day 40, MYBPC3-deficient hiPSC-CMs displayed decompensated state heart failure, marking the end-stage of the disease." (PMID 41158753, 2026). "The presence of bi-allelic truncating MYBPC3 mutations in patients is linked to neonatal cardiomyopathy, and can result in heart failure and mortality within the first year of life." (PMID 37445689, 2023). "MYBPC3-deleted hiPSC-CMs revealed the characteristics of heart failure, which exhibited increased contractility at 30 days but decreased at 40 days." (PMID 41158753, 2026). "Over the last two decades, more than 500 MYBPC3 mutations have been found, and the association of MYBPC3 mutations with developing HCM and heart failure (HF) has been intensively studied." (PMID 36854776, 2023). "Conversely, MyBPC3, another myocardial injury marker, is associated with heart failure, persistent AF, and hypertension but not with sex." (PMID 40496590, 2025). "Heart failure was associated with FGF23, IGFB-7, GDF-15, IL-6, and MyBPC3." (PMID 40496590, 2025). "The patient who died from heart failure had the MYBPC3 variant c.1226 + 6T > C, and the remaining had a negative molecular study." (PMID 31179125, 2019). "For example the 25 bp deletion in the gene encoding MYBPC3, present in ∼4% of people from the Indian subcontinent but not present in Europeans, confers an ∼7 fold risk of heart failure." (PMID 25115870, 2014). "Individuals with MYBPC3 missense VUS predicted to disrupt subdomain folding (STRUM+) present a high incidence of adverse clinical outcomes, including ventricular arrhythmias, heart failure, all-cause mortality, atrial fibrillation, and stroke, similar to pathogenic MYBPC3 variants." (PMID 37445689, 2023). "Therefore, 25 bp deletion in MYBPC3 may represent a genetic marker for cardiac failure in CAD patients from Southeast Asia." (PMID 21915287, 2011). "G3BP1-Suc level was diminished in Myosin binding protein C3 (Mybpc3) knockout and transverse aortic constriction (TAC) operated mice, which developed heart failure (HF)." (PMID 42107065, 2026). "Studies have shown that AAV9 enables broad myocardial distribution following intravenous or intracoronary injection and has demonstrated superior performance in delivering therapeutic genes such as SERCA2a, cBIN1, MYBPC3, and S100A1 in various models of heart failure and inherited cardiomyopathies." (PMID 41179895, 2025).
cardiac hypertrophy (41 papers, 2010 to 2026). "Mice with MYBPC3 gene knockout or mutation, when treated with AAV-MYBPC3 gene transfer, demonstrated improvement of cardiac function and long-term prevention of cardiac hypertrophy." (PMID 40993768, 2025). "Genetic ablation of Mybpc3 causes myocardial disarray, impaired in vivo cardiac function, and reduces myofilament Ca2+ sensitivity, leading to cardiac fibrosis and hypertrophy in mouse models." (PMID 41155405, 2025). "In HCM troponin I and MYBPC3, mutations have been associated in some cases with more asymmetric septal hypertrophy, which corresponds to the finding in our study that the abundance of these proteins is strong in the intraventricular septum." (PMID 39202712, 2024). "introduced the full‐length MYBPC3 cDNA into abnormal cardiomyocytes induced by pluripotent stem cells from HCM patients caused by mutation of the MYBPC3 gene, hence increasing the cMyBP‐C expression level and successfully improving cardiac hypertrophy." (PMID 39465141, 2024). "One example is the MYBPC3 c.2149-1G>A mutation, which has been shown to be more frequently associated with hypertrophy of the anterior interventricular septum, preserved left ventricular ejection fraction, and atrial enlargement." (PMID 37445689, 2023). "Previous studies have shown that, in most cases, HCM with MYBPC3 gene mutations is a late onset disorder with mild myocardial hypertrophy, a lower rate of sudden cardiac death, and relatively benign disease progression." (PMID 35717150, 2022). "Based on a previous study, peptidomics were used to distinguish the proteins that correlated with cardiac hypertrophy in cats with MYBPC3 gene mutations." (PMID 35883329, 2022). "This study reports the first GWAS significant SNP (rs1052373) in MYBPC3 in association with endurance athlete status with a direct relevance to cardiac hypertrophy and contraction." (PMID 32612638, 2020). "In general, a single HCM-heterozygous mutation is sufficient to affect myocardialfunction and lead to hypertrophy; however, early studies have associated variants inthe MYBPC3 gene with incomplete penetrance, mild VH, low SCD riskand benign clinical evolution." (PMID 28538763, 2017). "Left ventricular hypertrophy (LVH) in HCM usually develops during adolescence, but particularly myosin binding protein C (MYBPC3) mutations are slower to manifest and mutation carriers often demonstrate onset of hypertrophy later in life." (PMID 27259862, 2016). "In mouse models, allele-specific silencing of mutant MYH6 suppressed the development of HCM, and exon skipping therapy to skip a mutated exon in the MYBPC3 gene using ASOs reduced levels of incorrectly spliced messenger RNA, producing stable functional proteins and preventing cardiac hypertrophy." (PMID 40993768, 2025). "Certain variants are “high-risk” in that they are associated with a more unfavorable prognosis, such as mutations in the MYH7 converter region or the c.2737+1 (IVS26) G>T mutation in the MYBPC3 gene (leading to exon 26 skipping, resulting in severe ventricular hypertrophy and a high risk of SCD)." (PMID 37686045, 2023). "MYBPC3 is linked to elite athlete heart remodeling during or after exercise, but it could also be linked to the phenotype of cardiac hypertrophy (HCM)." (PMID 37754829, 2023). "In the early stages of myocardial hypertrophy, MYBPC3 expression undergoes compensatory upregulation to maintain cardiac function." (PMID 40548957, 2025). "Consistent with the known phenotype of this model, our Mybpc3-KI mice demonstrated early-onset cardiac hypertrophy, typically developing shortly after birth." (PMID 40427020, 2025). "Studies have revealed that the administration of full-length WT Mybpc3 cDNA via the AAV vector in homozygous Mybpc3-targeted knock-in mice can effectively hinder the onset of cardiac hypertrophy and dysfunction by augmenting cMyBP-C protein levels." (PMID 37445689, 2023).